CHAC1 (ChaC glutathione specific gamma-glutamylcyclotransferase 1)
Diseases named in the same sentence as CHAC1 in open-access papers (continued):
Sharing a sentence is not in itself a finding about the gene and the disease.
cancer (continued). "In summary, while slightly elevated CHAC1 expression may increase malignancy of cancer cells, overexpressing CHAC1 with CP may kill cancer cells via prolonged PERK/IRE1α activation." (PMID 38785562, 2024). "As a cancer biologist, these insights highlight the potential of CHAC1 as a biomarker and therapeutic target, paving the way for novel strategies to manage oxidative stress-related pathologies and enhance the efficacy of cancer treatments." (PMID 39534397, 2024). "However, cancer cells often adapt to oxidative stress by upregulating CHAC1, which can help them manage and exploit oxidative environments, leading to increased resilience and survival." (PMID 39534397, 2024). "For instance, while inhibiting CHAC1 may enhance cancer cell sensitivity to treatments, it could also undermine its protective role in conditions like neurodegenerative diseases where ferroptosis and oxidative stress are detrimental." (PMID 39534397, 2024). "Targeting CHAC1 or pathways regulating its expression could improve the efficacy of existing cancer treatments." (PMID 39534397, 2024). "ChaC1’s involvement extends beyond cancer, impacting other diseases and cellular processes." (PMID 39534397, 2024). "For instance, CHAC1 inhibitors could help mitigate oxidative stress in neurodegenerative diseases, while activators could enhance cancer cell death." (PMID 39534397, 2024). "Recent research has highlighted the role of ChaC1 in cancer progression." (PMID 39534397, 2024). "Therapeutically, targeting CHAC1 could increase cancer cell sensitivity to ferroptosis, aiding in overcoming resistance to standard treatments." (PMID 39534397, 2024). "Increased CHAC1 levels induce ferroptosis and inhibit GC cell proliferation and survival, indicating that targeting the ATF4/CHAC1 axis could be a promising strategy for ferroptosis-based cancer therapy." (PMID 39534397, 2024). "Thus, m6A modification, through the action of ALKBH5, plays a crucial role in the regulation of CHAC1 and subsequent cancer cell behavior." (PMID 39534397, 2024). "CHAC1, an essential regulator of oxidative stress and ferroptosis, is increasingly recognized for its significant roles in these cellular processes and its impact on various human diseases and cancers." (PMID 39534397, 2024). "By modulating GSH levels, CHAC1 may help cancer cells manage oxidative stress, allowing them to survive under conditions that would typically induce cell death." (PMID 39534397, 2024). "Moreover, this review highlights that CHAC1 upregulation enhances cancer cell sensitivity to chemotherapeutic agents by promoting oxidative stress and cell death pathways, including apoptosis and ferroptosis." (PMID 39534397, 2024). "In cancer, CHAC1’s function varies depending on the tumor type." (PMID 39534397, 2024). "The basal level of CHAC1 expression is suppressed across most cancer cells that we tested." (PMID 37553341, 2023). "Recent studies found that CHAC1 activation might also promote cancer cell death, including ferroptosis or necroptosis." (PMID 37553341, 2023). "We then assessed the potential clinical relevance of CHAC1 in cancer immunotherapy." (PMID 37553341, 2023). "Additionally, data from the UCSC Cancer Genomics Browser8 showed that high ABCC1, CHAC1, and GSS expression was associated with decreased disease-specific survival (DSS) and progression-free interval (PFI) (p < 0.001)." (PMID 34386492, 2021). "The results indicated the differential expression of CHAC1 may play an important role in the immunotherapy of these cancers." (PMID 33728749, 2021). "CHAC1 has been shown to break glutathione into 5-oxoproline and cysteinyl-glycine (Cys-Gly), promoting the depletion of glutathione and stress-induced apoptosis in cysteine deprived cancer cells." (PMID 33218188, 2020). "ChaC1 is known as a novel prognostic marker in many types of cancer." (PMID 31878259, 2019). "Again, poorly differentiated cancers demonstrated higher CHAC1 levels (P=0.024)." (PMID 22108517, 2012).
cancer (continued). "Among these upregulated genes, Dennd4a, Nfil3, Hspa1b, Chac1, Ddit4, Mex3b, Lysmd3, and Zbtb10 are mainly involved in oxidative stress and inflammation response, whereas Plcxd2, Dusp1, Cep85l, and Dusp8 are generally considered as tumor‐suppressor genes by inhibiting proliferation of cancer cells." (PMID 40231790, 2025). "Developing CHAC1 as a biomarker could aid in diagnosing and prognosing cancers and other diseases." (PMID 39534397, 2024). "CHAC1, a newly discovered enzyme associated with γ-glutamyl cyclotransferase activity, could degrade intracellular GSH, which might cause oxidative stress and contribute to necroptosis and ferroptosis in cancer." (PMID 34284774, 2021). "In contrast to CHAC1, the general role of CHAC2 in cancer and programmed cell death remains elusive." (PMID 41488051, 2025). "Consistent with mRNA expression, ATF3, HO1, CHAC1, and PTGS2 are significantly up-regulated in cancer cells after challenging with Fe-EGCG@RSL3." (PMID 40530387, 2025). "Through a series of validations, we found that the ALKBH5/CHAC1/GSH axis has a role in regulating the level of ROS and apoptosis in cancer cells." (PMID 38007439, 2023). "We analyzed the expression of the four independent prognostic factors (FBXO6, PMAIP1, ERP27, and CHAC1) in BRCA and 32 other cancer types and observed that all four genes were highly expressed in BRCA." (PMID 37313465, 2023). "CHAC1’s role extends beyond cancer to non-malignant diseases, including neurodegenerative disorders, cardiovascular diseases, and inflammatory conditions." (PMID 39534397, 2024). "Consequently, CHAC1’s function in NSCLC highlights its dual role in supporting cellular metabolism and contributing to the vulnerability of cancer cells to ferroptosis." (PMID 39534397, 2024). "The relationship between CHAC1 and other ferroptosis markers, such as PTGS2 and ACSL4, further underscores its significance in the oxidative stress and cell death mechanisms pivotal to cancer progression and treatment strategies." (PMID 39534397, 2024). "Thus, CPEB1 regulates CHAC1 by modulating the TWIST1-ATF4 pathway, highlighting its role in ferroptosis and potential as a therapeutic target in cancer treatment." (PMID 39534397, 2024). "Similarly, the significantly downregulated genes included CHAC1, SLC7A11, PYCR1, PSPH, and DDIT4, among others, with these genes being involved in iron death, cancer cell expansion, and apoptosis (15, –, 19)." (PMID 38299864, 2024). "In pan-cancer analysis of 32 cancer species, ABCC1, CHAC1, and GSS may act as hallmarks to activate tumor immune reactions and reshape the tumor environment in LGG, LIGC, BRAC, LUAD, LUSC, and UVM." (PMID 34386492, 2021). "We next tested the generality of CHAC1 upregulation in response to erastin, and observed that across a panel of 13 cancer cell lines, treatment with erastin, but not the apoptosis-inducer STS, resulted in a significant increase in CHAC1 expression." (PMID 24844246, 2014). "CHAC1 is a known cation transport regulator and apoptosis mediator; however, its effects on cancer cell apoptosis have never been examined." (PMID 23342279, 2012). "Thus, like CHAC1, CHAC2 represents an intriguing and complex target for further cancer research." (PMID 41488051, 2025). "The therapeutic potential of CHAC1 extends beyond cancer, impacting various non-malignant diseases." (PMID 39534397, 2024). "Thus, CHAC1 serves a dual role: it preserves mitochondrial function by ensuring a cysteine supply under nutrient stress, but it also facilitates ferroptosis by maintaining ETC activity, highlighting its potential as a therapeutic target in cancer treatment." (PMID 39534397, 2024). "In addition, although CHAC1 is known as an apoptotic mediator, its effects on cancer cell apoptosis have not been examined." (PMID 23342279, 2012). "However, the contribution of CHAC1 to platinum resistance in cancer has not been studied." (PMID 39893168, 2025).
cancer (continued). "Furthermore, CHAC1 was among the most upregulated genes in SCC and glioblastoma cells (>16 and 25-fold, respectively) following treatment with PAM that was sizably larger than in keratinocytes, indicating an intense degree of redox stress aggravating the UPR in cancer cells that led to apoptosis." (PMID 38785562, 2024). "Interestingly, low-dose AF-induced enhancement of Bz-mediated ISR and CHAC1 upregulation observed in MDA-MB 435 S cells was not seen in MCF10A cells, suggesting that TrxR1/proteasome inhibition preferentially kills cancer cells via cancer-selective aggravation of proteotoxic stress." (PMID 36658130, 2023).
tumor (40 papers, 2012 to 2025). "CHAC1, an enzyme associated with the activity of γ-glutamylcyclotransferase, plays a crucial role in promoting the ferroptosis of tumor cells by degrading intracellular GSH." (PMID 39335604, 2024). "In line with this, CHAC1 deficiency in tumor cells impaired the infiltrations of CD8+ T cells, and expressions of IFNγ and TNFα in CD8+ T cells and CD4+ T cells that were all induced by the combination therapy." (PMID 37553341, 2023). "CHAC1 over-expression sensitizes the tumor to CTL-mediated cytotoxicity, whereas CHAC1 loss causes CTL resistance in vitro and immunotherapy resistance in vivo." (PMID 37553341, 2023). "The combination therapy greatly suppressed tumor growth in CHAC1 wildtype tumors, but its therapeutic efficacy was significantly impaired in CHAC1 deficient tumors." (PMID 37553341, 2023). "The aberrant expression of CHAC1 surprisingly has been linked with both tumor suppression as well as tumor progression." (PMID 36568153, 2022). "Critically, dysregulation of CHAC1 expression is intricately linked to tumor drug resistance." (PMID 40860820, 2025). "The prognostic significance of CHAC1 mRNA expression determined specifically for younger women could provide indication that strong CHAC1 mRNA expression may be associated with an earlier development of more aggressive tumours." (PMID 22108517, 2012). "A high CHAC1 mRNA expression was also associated with advanced tumour stage (P=0.026)." (PMID 22108517, 2012). "GSH is also susceptible to enzymatic degradation by extracellular γ‐glutamyltranspeptidase (GGT) or intracellular γ‐glutamylcyclotransferase (ChaC1), which are often upregulated in tumor tissues." (PMID 41498011, 2025). "Elevated CHAC1 expression in LUAD correlates with aggressive tumor progression and poor patient prognosis." (PMID 41488051, 2025). "CDX models formed by GDIL overexpression HCT116 cells promoted tumor survial under oxaliplatin treatment, while further ectopic expression of CHAC1 alleviated tumor resistance." (PMID 39893168, 2025). "Preclinical intervention confirms that disrupting this axis (miR-432-5p inhibition) restores CHAC1 expression and augments docetaxel-induced tumor regression by 52%." (PMID 40860820, 2025). "This loop’s clinical relevance was confirmed in vivo: in a CAF/PC-3 cell co-transplant mouse model, targeted silencing of miR-432-5p restored CHAC1 expression in tumor tissue by 3.2-fold (P<0.01) and enhanced DTX tumor suppression efficacy by 52%." (PMID 40860820, 2025). "Although studies have revealed the important roles of CHAC1 in tumor cell physiology and ferroptosis, many questions remain to be further explored." (PMID 40860820, 2025). "The GEPIA database showed that CHAC1 expression in tumor tissues was significantly lower than that in normal tissues." (PMID 39819316, 2025). "The elevated CHAC1 expression in LUAD promotes tumor proliferation and metastasis by enhancing glycolysis, lactate production, and ATP generation through regulation of pyruvate kinase M2 (PKM2)." (PMID 41488051, 2025). "The precise impact of CHAC1 on the tumor microenvironment (TME) represents a significant gap in current understanding, despite its established roles in enhancing ER stress, inducing ferroptosis, and reducing drug resistance." (PMID 40860820, 2025). "Current research delineates a CHAC1-centric resistance regulatory network encompassing both cell-autonomous mechanisms and tumor microenvironment (TME) interactions." (PMID 40860820, 2025). "CHAC1, a critical component of this pathway, is instrumental in regulating this cell death process, effectively inhibiting tumor growth in both laboratory and animal models." (PMID 39534397, 2024).
tumor (continued). "Since the epithelial–mesenchymal transition (EMT) process is integral to tumor metastasis, we further investigated the relationship between CHAC1 expression and EMT." (PMID 39368995, 2024). "MIA3 exerts tumour-promoting effects in HCC by binding to the CHAC1 protein and promoting glutathione biodegradation." (PMID 37948019, 2024). "In vivo experiments confirmed that knocking down miR-432-5p in CAFs enhanced CHAC1 expression, increased ferroptosis, and improved the efficacy of docetaxel in reducing tumor growth." (PMID 39534397, 2024). "Phenotypically, CHAC1 overexpression enhanced the proliferation, migration, invasion, tumor sphere formation, and glycolysis ability of LUAD cells, resulting in tumor growth both in vitro and in vivo." (PMID 39368995, 2024). "Overexpression of ARHGAP6, which inhibits these pathways, results in increased CHAC1 expression, thereby promoting ferroptosis and inhibiting tumor growth." (PMID 39534397, 2024). "By utilizing tissue microarray and data from The Cancer Genome Atlas and Gene Expression Omnibus, we found that CHAC1 expression was markedly higher in LUAD tissues than in non-tumor tissues, and was positively correlated with poor prognosis." (PMID 39368995, 2024). "Compared to the control group, the overexpression of CHAC1 in A549 cells increased the size and number of tumor spheres." (PMID 39368995, 2024). "On the one hand, CHAC1 demonstrates tumor-suppressive properties by promoting apoptosis and ferroptosis in response to cellular stress, such as oxidative stress and ER stress." (PMID 39534397, 2024). "Genes like miR-5069 and glutathione-specific gamma-glutamylcyclotransferase 1 (CHAC1) also regulate ferroptosis, inhibiting tumor growth through the modulation of ROS and iron-dependent pathways." (PMID 39664391, 2024). "Taken together, the knockdown of CHAC1 in RMS tumor cells decreased cell proliferation and increased apoptosis, recapitulating the effects of the combination therapy with VCR and RCM1." (PMID 36816948, 2023). "By conducting CHAC1 knockdown experiments, we have confirmed that CHAC1 plays a role in suppressing tumor growth and metastasis in GC." (PMID 38007439, 2023). "We further manipulated CHAC1 expression in multiple tumor cell lines and found that CHAC1 knockout or knockdown was delayed, while CHAC1 overexpression accelerated GSH depletion and ferroptosis onset." (PMID 37553341, 2023). "We also explored how CHAC1 expression is differently regulated by long-term or short-term methionine deprivation in tumor cells." (PMID 37553341, 2023). "Taken together, these results reveal that tumor CHAC1 affects antitumor immunity in vivo via the regulation of tumor ferroptosis." (PMID 37553341, 2023). "We confirmed that ALKBH5 overexpression within tumor lesions increased the expression of the proliferation marker Ki67 while reducing CHAC1 expression." (PMID 38007439, 2023). "CHAC1, in addition to NOX4 and GPX4, is considered to be a hallmark of ferroptosis and has been reported to be involved in tumor cell death via the induction of ferroptosis." (PMID 37371096, 2023). "To determine the role of CHAC1 in RMS tumor cells, we generated a shRNA lentivirus against Chac1 (shChac1) and transduced Rd76-9 cells to inhibit Chac1 expression in vitro." (PMID 36816948, 2023). "Consistent with human cells, we manipulated murine CHAC1 by transduction of two different guide RNAs in multiple mouse tumor cell lines including Hepa1-6, B16F10, MC38 and PanO2." (PMID 37553341, 2023). "Depletion of CHAC1 decreased the numbers of viable Rd76-9 tumor cells in culture compared to control tumor cells." (PMID 36816948, 2023). "In terms of grade alone, CBS, CD44, and CHAC1 increased with tumor grade, while HMGCR was decreased." (PMID 35422048, 2022).